SMARCA4 (SWI/SNF related BAF chromatin remodeling complex subunit ATPase 4)
Diseases named in the same sentence as SMARCA4 in open-access papers (continued):
Sharing a sentence is not in itself a finding about the gene and the disease.
cancer (continued). "Therefore, PROTACs that selectively target the non-functional BRD of SMARCA2/4 presents a potential avenue for exploiting the susceptibilities of cancer cells that rely on SMARCA2 or SMARCA4 for their survival." (PMID 38389844, 2024). "A better understanding of the relationship between SMARCA4 deficiency and cancer development could support the development of new therapeutic strategies." (PMID 38542211, 2024). "All seven SMARCA4/KRAS co-mutation NSCLC publications in this review showed either a significantly worse PFS or OS as compared to SMARCA4 WT/KRAS mutation analyses across standard-of-care cancer treatments or within a specific treatment analysis (i.e., KRAS G12C inhibitor, ICIs, or non-ICIs)." (PMID 39063938, 2024). "Overall, our data may have future clinical implications, offering a potential therapeutic option for patients harboring SMARCA4 mutation cancers because of their efficacy and less frequent IV dosing." (PMID 38755248, 2024). "While the evidence might not be deemed conclusive, the findings offer encouraging signals that targeting the loss of SMARCA4 may represent an effective approach for treating this particularly aggressive cancer type." (PMID 39439958, 2024). "Overall, these data indicated that SMARCA4 may act as a tumor suppressor, and its loss-of-function mutation may promote cancer." (PMID 39580422, 2024). "SMARCA4 mutations occur in approximately 5–7% of all human cancers and 7–11% of NSCLC cases." (PMID 39063938, 2024). "Mutations of SMARCA4 have been identified in a range of cancer types, including ovarian cancer, melanoma, and non-small-cell lung cancer, with an occurrence rate sitting at around 11% across various human cancers." (PMID 38675453, 2024). "Nonetheless, our case contributes a layer of evidence that a germline SMARCA4 pathogenic variant, may have broader implications in cancer predisposition beyond the currently recognized associations." (PMID 39439958, 2024). "The anti-cancer effects of AU-15330 were attributed to the loss of SMARCA4." (PMID 38390898, 2024). "In many cancers SMARCA4 is found to be mutated and likely acts as an oncogene." (PMID 38446332, 2024). "PRT3789 is another potent and selective SMARCA2-targeted degrader that demonstrated synthetic lethality in SMARCA4-deficient cancers in vitro and in vivo and is currently in Phase I clinical trials for patients with SMARCA4 mutant solid tumors that express SMARCA2." (PMID 38390898, 2024). "Contemporary studies highlight the importance of oxygenation in ATP production for specific cancers, which may be detected by genetic biomarkers such as SMARCA4 mutations." (PMID 39132153, 2024). "Indeed, SMARCA4-deficient cancer cells showed sensitivity to inhibition of methyltransferase EZH2, the catalytic subunit of PRC2." (PMID 39697230, 2024). "Gastric SMARCA4-deficient carcinoma could be differentiated from gastric SMARCA4-UT based on gland architecture, cellular cohesion and diffuse strong keratin expression." (PMID 38877473, 2024). "Gastric SMARCA4-deficient tumors may include gastric SMARCA4-deficient carcinoma and gastric SMARCA4-deficient undifferentiated tumor (SMARCA4-UT)." (PMID 38877473, 2024). "The diagnosis of SMARCA4 (BRG1))-deficient carcinoma was confirmed by biopsy." (PMID 38989233, 2024). "Gastric SMARCA4-deficient carcinoma could be distinguished from gastric SMARCA4-UT by gland architecture, cellular cohesion, and diffuse strong keratin expression." (PMID 38877473, 2024). "SMARCA4 (BRG1)-deficient carcinoma is a rare clinical disease; both cases invade the structures of the skull base and might be utilized for physicians' reference and knowledge." (PMID 38989233, 2024). "The final pathological diagnosis was SMARCA4 (BRG1)-deficient carcinoma." (PMID 38989233, 2024). "SMARCA4(BRG1) is a deficient carcinoma that invades the brainstem and middle skull base." (PMID 38989233, 2024). "Histologically, SMARCA4-deficient carcinomas are undifferentiated, hence closely akin to SNUC." (PMID 38491228, 2024).
cancer (continued). "Pathological analysis indicated a SMARCA4 (BRG1))-deficient carcinoma." (PMID 38989233, 2024). "We discovered that a large subset of cancers of unknown primary (>10%) have SMARCA4 deficiency and that these cancers can be accurately predicted from their whole-genome accumulation of SBS signature 4 or SBS signature 27 mutations." (PMID 36883553, 2023). "Since SMARCA4-deficient tumors in thoracic malignancies were reported in 2015, SMARCA4 expression and its genetic mutations have received attention in various cancers." (PMID 37626774, 2023). "Several synthetic lethal relationships have been described in altered SWI/SNF-driven cancers whereby cell viability upon the loss of one subunit (e.g., SMARCA4, SMARCB1, ARID1A) uniquely relies on the presence of either other SWI/SNF paralog subunit or a downstream gene or cellular pathway." (PMID 36810086, 2023). "The discovery of SMARCA4 loss in this type of cancer will help in identifying patients with SCCOHT and might lead to new options for targeted drug therapies." (PMID 37568608, 2023). "Furthermore, supplementation of alanine, also imported by SLC38A2, restricts glutamine uptake through competition and selectively induces death in SMARCA4/2-deficient cancer cells." (PMID 37210563, 2023). "In the present study, we uncover that SMARCA4/2 loss triggers a metabolic shift in cancer cells, resulting in a preference for utilizing glutamine over glucose as the primary carbon source to fuel the tricarboxylic acid (TCA) cycle and sustain oxidative phosphorylation (OXPHOS)." (PMID 37210563, 2023). "Therefore, the strategy of targeting SMARCA2 to treat cancers with SMARCA4 mutations has attracted a lot of attention." (PMID 37496997, 2023). "SMARCA4-mutated cancers have a DNA repair vulnerability that can be exploited therapeutically." (PMID 38090508, 2023). "Together, these data demonstrate that alanine could be used to target glutamine dependency in SMARCA4/2-deficient cancer cells by suppressing SLC38A2-mediated glutamine import and consequently, inhibiting glutaminolysis and OXPHOS." (PMID 37210563, 2023). "Thus, there is therapeutic potential in targeting the functional domains of SMARCA2 and SMARCA4 in some cancer contexts, particularly when there is a deficiency in one ATPase." (PMID 35323214, 2022). "However, molecular function of this gene product is ATP-dependent chromatin remodeling and overall transcriptional activation, and SMARCA4 mutations are linked with many cancers." (PMID 35359606, 2022). "We aimed to achieve orally bioavailable molecules that selectively degrade the BAF Chromatin Remodelling complex ATPase SMARCA2 over its closely related paralogue SMARCA4, to allow in vivo evaluation of the synthetic lethality concept of SMARCA2 dependency in SMARCA4-deficient cancers." (PMID 36216795, 2022). "In particular, SMARCA4 is one of the most frequently aberrant chromatin remodeling ATPases in cancer, being altered in approximately 5–7% of all human malignancies; moreover, SMARCA4 genomic alterations and loss of SMARCA4 expression have been observed in some tumors." (PMID 35163487, 2022). "First, by choosing an NGN PAM target closer to the edit of interest compared to a site with an NGG PAM, we introduced the substitution R350C (which mimics a human cancer mutation) in the C. elegans protein SWSN-4/SMARCA4 with an efficiency of 10% among dpy-10 co-edited animals." (PMID 35552388, 2022). "These include NUT carcinoma, SMARCB1-deficient carcinoma, and SMARCA4 deficient carcinoma." (PMID 35326613, 2022). "SMARCA4 deficient carcinoma is vanishingly rare in the sinonasal region." (PMID 35326613, 2022). "Concerning less common histologic types, pulmonary sarcomatoid carcinomas and SMARCA4-deficient carcinoma with its dedifferentiated counterpart, the SMARCA4-deficient undifferentiated thoracic tumor (SMARCA4-UT), are significantly associated with worse prognosis." (PMID 35326552, 2022).
cancer (continued). "SMARCA4-deficient carcinoma is the major consideration if SMARCA4 loss is identified in biopsies." (PMID 35307773, 2022). "Consequently, stimulation of ITPR3 expression through SMARCA2 reactivation by HDACi enhanced chemotherapy response in SMARCA4/2-deficient cancer cells." (PMID 34518526, 2021). "Our study provided proof-of-principle data supporting that HDACi may be a potential therapeutic strategy to stimulate ITPR3 transcription through SMARCA2 reactivation and sensitize SMARCA4/2-deficient cancers to chemotherapy." (PMID 34518526, 2021). "However, the downstream regulation according to SMARCA4 mutation is unclear and controversial in various cancers." (PMID 34771636, 2021). "Furthermore, SMARCA4 is aberrantly expressed in various cancers and significantly associated with MMR, MSI, DNA methylation, and TMB." (PMID 34675941, 2021). "While this requires further studies, these data support that reduced IP3R3 expression in SMARCA4/2-deficient cancers may directly contribute to the tumorigenesis through suppression of apoptosis." (PMID 34518526, 2021). "Similarly, experimental suppression of SMARCA2 has been shown to be selective lethal to SMARCA4-deficient/SMARCA2 proficient cancer cells." (PMID 34518526, 2021). "Our findings elucidate the contribution of SMARCA4/2 to Ca2+-dependent apoptosis induction, which may be exploited to enhance chemotherapy response in SMARCA4/2-deficient cancers." (PMID 34518526, 2021). "Given that SCCOHT is a SMARCA4 mutation-driven, highly aggressive monogenic cancer type, it may reflect the enhanced immunogenicity mediated by loss of SMARCA4 function." (PMID 33419967, 2021). "In contrast, the SMARCA4 paralogue SMARCA2 is less frequently mutated in cancer." (PMID 33941852, 2021). "The differential diagnosis of poorly differentiated SNSCC is challenging and includes: SNUC (including those characterized by molecular identifiers, such as IDH2-mutant SNUC, SMARCA4-deficient carcinoma, and SMARCB1/INI1-deficient carcinoma), NECs, and adenoid cystic carcinoma." (PMID 34200193, 2021). "Loss of function of SMARCA4 characterizes the SMARCA4-carcinomas." (PMID 34287240, 2021). "Indeed, histone methyltransferase EZH2 (part of the PRC2 complex) is essential for survival and growth of SMARCA4-deficient cancer cells." (PMID 31996670, 2020). "SMARCA4 mutations were present in a diverse set of cancer types at frequencies up to 16%." (PMID 33144586, 2020). "Moreover, high SMARCA4 mRNA levels are associated with better surgical resectability, especially in high-grade cancers." (PMID 33230143, 2020). "However, it has been reported that inactivating mutations in SWI/SNF subunits (ARID1A, PBRM1, SMARCB1, and SMARCA4) also sensitize cancer cells to T cell-mediated destruction." (PMID 32649682, 2020). "In more recent studies, when copy number analysis was used in combination with expression profiling to identify cancer‐associated mutations, the results revealed that SMARCA4 is up‐regulated in HCC and that its level is markedly correlated with cancer progression among HCC patients." (PMID 32162380, 2020). "Finally, one limitation of this study is our ability to address the potential for concurrent loss of SMARCA2 in SMARCA4-mutant cancers." (PMID 33144586, 2020). "A portion of the cancer-associated SMARCA4 mutations occur within the ATPase domain." (PMID 31123059, 2019). "While the lung tumour of the father in Family 1 showed loss of expression of SMARCA4, it is unclear whether the cancer was related to the SMARCA4 germline mutation; the patient was a smoker and many lung tumours display loss of SMARCA4 expression." (PMID 27866340, 2017). "We speculate that the other alterations required for cancer cells to survive loss of SMARCA4 may also contribute to sensitivity to AURKA inhibitors." (PMID 28102363, 2017). "However, SMARCA4-deficient carcinomas are much rarer and mainly involve the nasal cavity." (PMID 38989233, 2024).
cancer (continued). "To assess the role of germline pathogenic variants (PVs) in SMARCA4 and further established OC predisposition genes in early onset OC, we investigated a clinical cohort of 206 unrelated index patients using an extended panel of 25 (candidate) cancer predisposition genes." (PMID 37345881, 2023). "Smoking, and possibly other unmeasured lifestyle factors, might have led male patients to have worse PS and CCI at the time of diagnosis of the SMARCA4-mutated malignancy and could be partially responsible for their worse OS by accelerating cancer progression even before their diagnosis." (PMID 37345003, 2023). "Thus, while SWI/SNF deficiencies have been widely associated to cancer progression, the mechanism by which SMARCA4/2-deficient cancer cells have adapted to resist chemotherapy is unknown." (PMID 34518526, 2021). "In addition to IP3R3, other common targets of SMARCA4/2 may also play a role in altered Ca2+ homeostasis impacting apoptosis, which could serve as potential drug targets in SMARCA4/2-deficient cancers and will require further studies." (PMID 34518526, 2021). "Likewise, SMARCA2 dependency was observed in SMARCA4-deficient cancer cells." (PMID 31769422, 2019). "Thus SMARCA4-deficient cancers still lack rationalized and targeted treatment options." (PMID 30718512, 2019). "A sgRNA-resistant SMARCA4 expression construct in which the SMARCA4 bromodomain is replaced with the bromodomain of BRD9 (SMARCA4res-BDBRD9) was designed to determine whether acute degradation of SMARCA4 represents a therapeutic approach against SMARCA2-deficient cancers." (PMID 31406271, 2019). "This insight provides valuable information about the functional significance of G4 structures and their interaction with SMARCA4, particularly in the context of cancer." (PMID 42002776, 2026). "Despite advancements in cancer therapy, effective treatments for SMARCA4‐UT remain elusive, with traditional cytotoxic agents showing limited efficacy." (PMID 41577374, 2026). "SMARCA4‐deficient cancer cells are highly dependent on SMARCA2 for survival, and targeting SMARCA2 in SMARCA4‐deficient cancers is expected to produce strong synthetic lethal effects." (PMID 41049269, 2025). "By summarizing the current evidence, we aim to clarify the clinical landscape and highlight unmet needs in the diagnosis and management of SMARCA4-altered cancers." (PMID 40867304, 2025). "On the other hand, the sensitivity of ARID1A-deficient cancer cell lines to CBP/p300 dual inhibitors was intermediate between SWI/SNF WTs and the sensitive genotypes (SMARCA4/SMARCA2-deficient and SS18–SSX fusion)." (PMID 39625239, 2025). "SMARCA4 is a crucial component of the SWI/SNF chromatin‐remodeling complex, and its mutations have been implicated in several cancers." (PMID 40926327, 2025). "Targeting of the SMARCA4 LOF mutation found in NSCLC and many other cancers serves as an excellent example of the potential of this approach." (PMID 41008934, 2025). "They used lab experiments and mouse models to show that reducing GAS5 or SMARCA4 can slow down cancer growth." (PMID 40451925, 2025). "Despite increasing clinical awareness, the full spectrum of SMARCA4-altered cancers remains incompletely defined, and therapeutic guidelines are lacking due to the rarity of reported cases and the absence of prospective clinical trials." (PMID 40867304, 2025). "BRG1 mutation and loss of function are important diagnostic abnormalities for the unique ovarian (SCCOHT) and thoracic (SMARCA4-DTS) cancers and are detected in increasing numbers of other malignancies." (PMID 41008934, 2025). "SMARCA4 is one of the most frequently altered chromatin remodeling ATPases in cancer, significantly impacting transcriptional regulation by disrupting histone–DNA interactions in an ATP-dependent manner." (PMID 40416876, 2025).
cancer (continued). "While thoracic SMARCA4-deficient undifferentiated tumors are relatively well described, the full spectrum of SMARCA4-altered cancers across different organs and their therapeutic responses remains poorly understood." (PMID 40867304, 2025). "Of the genomic alterations involving alleles encoding BAF subunits, those occurring at the SMARCA4 and ARID1A loci have been the most thoroughly investigated in human cancer." (PMID 41387924, 2025). "Researchers found that GAS5 helps cancer grow by interacting with other molecules such as miR-423-3p and SMARCA4." (PMID 40451925, 2025). "Given its relevance for cancer and the availability of SMARCA4 inhibitors, we decided to investigate further their suitability as a target to enhance NK-mediated killing of senescent cells." (PMID 39813356, 2025). "Recently, a role for BRG1 (SMARCA4) in regulating gene expression and its frequent alteration in various cancers, including NSCLC, has been reported." (PMID 41514577, 2025). "Results of histopathological analysis revealed a heterogenous malignant neoplasia with embryonal characteristics and immunohistochemical loss of nuclear SMARCB1/INI1 expression, while SMARCA4/BRG1 staining was retained." (PMID 41168858, 2025). "SMARCA4 is a component of the SWI/SNF chromatin remodeling complex, and it is often mutated in cancer." (PMID 39813356, 2025). "For instance, germline missense variants in SMARCA4 cause CSS, while germline null variants are responsible for cancers." (PMID 40697538, 2025). "SMARCA4-deficient undifferentiated uterine sarcoma (SDUS) is a rare, sporadic malignant tumor of mesenchymal origin of the uterus, which has highly aggressive and poor prognosis." (PMID 40826772, 2025). "In this study, we reported an atypical case of DEC composed of SMARCA4-deficient UEC and PEGT-carcinoma and reviewed its clinicopathological features." (PMID 40094007, 2025). "We present an unusual DEC case with SMARCA4-deficient UEC and PEGT-carcinoma, reviewing its clinicopathological profile." (PMID 40094007, 2025). "This approach has notably enhanced our understanding of the molecular interactions and clinical relevance of SMARCA4 mutations in GEA, contributing to a deeper insight into the molecular characterization of this cancer type." (PMID 38610978, 2024). "Nevertheless, the molecular mechanisms of SMARCA4 in cancer development are not yet fully understood." (PMID 38542211, 2024). "More research on the mechanism of SMARCA4’s role in different cancer types is needed in future studies." (PMID 39697230, 2024). "Thoracic SMARCA4-UTs are high-grade malignant neoplasms that significantly affect the thorax of adults, are characterized by an undifferentiated or rhabdoid phenotype, and displays a deficiency of SMARCA4 (BRG1)." (PMID 38374950, 2024). "Meanwhile, the SMARCA4 gene pool for children with cancer (reported for 10 studies, n = 3784) identified six LoF variants." (PMID 38424437, 2024). "Radical surgery is the preferred method for treating malignant tumors; however, SMARCA4-UT often shows local invasion and distant metastasis, making only a few early stage patients eligible for surgery." (PMID 38903719, 2024). "SMARCA4 deregulation results in a decrease in actin stress fibers and thick actin bundles in the cell body, altering cancer cell morphology." (PMID 38542211, 2024). "We conducted NGS using the Ion Torrent platform with a custom panel covering 50 cancer-related genes, including SMARCA4 and KRAS." (PMID 39777351, 2024). "Recent research has however found that SMARCA4 likely promotes cancer growth and is a good target for cancer treatment." (PMID 38446332, 2024). "By exploring the predictability function in DepMap, we observed that low levels of SMARCA2 are positively correlated with SMARCA4 CRISPR knockout effects across all cancer cell lines." (PMID 39174852, 2024). "We found that SMARCA4 was indeed overexpressed in cancer patients by 59% (p = 1.81e-16, adj p = 1.71e-15)." (PMID 38446332, 2024).